DPP4 (dipeptidyl peptidase 4)
Diseases named in the same sentence as DPP4 in open-access papers (continued):
Sharing a sentence is not in itself a finding about the gene and the disease.
diabetes (continued). "Among the dipeptidyl peptidase-4 (DPP-4) inhibitors that are widely used, sitagliptin is the first to be approved for patients with type 2 diabetes mellitus (T2DM) on insulin therapy." (PMID 26124906, 2015). "Dipeptidyl peptidase-4 (DPP-4) inhibitors, such as saxagliptin, have gained a rapid growth in use in the treatment of type 2 diabetes mellitus in the past decade." (PMID 26290759, 2015). "Therefore, DPP-4 inhibitors may be useful in the management of hyperglycemia in patients with glucocorticoids-induced diabetes, which is characterized by normal or mild increase in fasting plasma glucose levels and a remarkable increase in postprandial glucose levels." (PMID 25883713, 2015). "Since GLP-1 and GIP are rapidly degraded and inactivated by dipeptidyl peptidase-4 (DPP-4), inhibition of DPP-4 and/or DPP-4-resistant GLP-1 analogues have been proposed as a potential target for the treatment of diabetes." (PMID 25582643, 2015). "In contrast, another short-term study showed that DPP-4 inhibitors, including sitagliptin or alogliptin, attenuated endothelial function as evaluated by FMD after 6 weeks of treatment in patients with diabetes." (PMID 25074318, 2014). "Incretin-based compounds, including glucagon-like peptide-1 (GLP-1) analogues and dipeptidyl peptidase-IV (DPP-4) inhibitors, have been available for the treatment of diabetes in Japan from 2009." (PMID 24884787, 2014). "The recently developed treatment against diabetes, based on GLP-1 receptor agonists or dipeptidyl peptidase-4 (DPP4) inhibitors (the enzyme responsible of GLP-1 inactivation), have been shown to induce beneficial effects on beta cell function." (PMID 23737653, 2013). "Despite these positive effects, GLP-1 augmentation as a strategy to treat diabetes was deemed impractical, because GLP-1 is rapidly degraded in the circulatory system, by the enzyme dipeptidyl peptidase-IV (DPP-4), with a half-life of less than 2 minutes." (PMID 23256660, 2013). "Along this line, dipeptidyl peptidase-4 (DPP-4) inhibitors were developed to stabilize endogenous GLP-1, an approach which is effective in treating obesity and diabetes." (PMID 23700406, 2013). "We investigated sera of patients with type 2 diabetes mellitus (T2DM) treated with metformin and sulfonylurea, insulin glargine or a DPP-4 inhibitor (DPP4i)." (PMID 24004910, 2013). "Two other drug families that were recently approved for treatment of diabetes mellitus are the Glucagone like Peptide-1 (GLP-1) analogues and Di Peptidyl Peptidase IV (DPP4) inhibitors, both act via the incretin pathway." (PMID 23537430, 2013). "The prescription of more expensive diabetes drugs, such as GLP-I analogues, DPP-4 inhibitors and oral combination drugs, was rather low among our study participants." (PMID 22838970, 2012). "Dipeptidyl Peptidase-4 (DPP-4) inhibitors and Glucagon-like Peptide One (GLP-1) Receptor Agonists (GLP-1RAs) are both recommended by clinical guidelines for the glycemic management of patients with type 2 diabetes mellitus (T2DM) across the disease spectrum." (PMID 41590243, 2026). "This review aims to provide a comprehensive overview of plant-derived compounds that exhibit inhibitory activity against key diabetes-related enzymes, including α-glucosidase, α-amylase, protein tyrosine phosphatase 1B (PTP1B) and dipeptidyl peptidase-4 (DPP-4)." (PMID 42195389, 2026). "Ever use of metformin, insulin, sulfonylureas, DPP‐4 inhibitors, and SGLT‐2 inhibitors was associated with worse overall survival compared to patients who did not develop prediabetes/diabetes." (PMID 41287203, 2026). "CGM use in conjunction with ≥ 1 of five anti‐diabetes medication classes: metformin, sulfonylureas, sodium‐glucose cotransporter‐2 (SGLT2) inhibitors, dipeptidyl peptidase‐4 (DPP‐4) inhibitors and/or glucagon‐like peptide‐1 receptor agonists (GLP‐1 RAs) was required." (PMID 40851538, 2025).
diabetes (continued). "This suggests that the combination of a DPP-4 inhibitor and an SGLT2 inhibitor may be a viable therapeutic option for managing diabetes mellitus in patients with CMT, warranting further investigation in larger studies due to the rarity of this comorbidity." (PMID 40951209, 2025). "Of the patients with pre-transplant diabetes and those who developed de novo diabetes after transplantation (n = 44), 5 patients were taking sodium–glucose cotransporter 2 (SGLT2 inhibitors), and 4 patients were taking dipeptidyl peptidase-4 inhibitors at the end of the study." (PMID 41156001, 2025). "Dipeptidyl peptidase-4(DPP-4)inhibitors can effectively improve blood glucose control in individuals with T2DM and notably decrease glucose variability when compared to alternative oral medications for diabetes." (PMID 40620795, 2025). "The combination of DPP-4 and SGLT2 inhibitors may be a promising option for treating diabetes mellitus in patients with CMT and compromised muscle mass." (PMID 40951209, 2025). "In patients with obesity and without diabetes, the PP protein expression showed a positive correlation with abdominal pain (r = 0.408, p = 0.043), while DPP-4 protein expression exhibited a positive correlation with indigestion (r = 0.407, p = 0.043)." (PMID 40142315, 2025). "Glucose homeostasis (green)—Two peptides exhibited dipeptidyl peptidase 4 (DPP-IV) inhibitory activity, which is beneficial for glucose metabolism and may help manage diabetes." (PMID 40077579, 2025). "People living with type 2 diabetes are often prescribed multiple non‐insulin anti‐diabetes medications, such as metformin, sulfonylureas, sodium‐glucose cotransporter‐2 (SGLT2) inhibitors, dipeptidyl peptidase‐4 (DPP‐4) inhibitors and glucagon‐like peptide‐1 receptor agonists (GLP‐1 RAs)." (PMID 40851538, 2025). "Due to the rapid degradation of native GLP-1 by dipeptidyl peptidase-4 (DPP-4), resulting in a short half-life, GLP-1 receptor agonists (GLP-1RAs) have been developed to provide a more effective and sustained therapeutic option for diabetes management." (PMID 40149704, 2025). "This constraint limits our ability to robustly assess the direct effects of DPP4 inhibition on CVD independent of type 2 diabetes mellitus (the IV number can be used in multi-GRAPPLE is less than 2)." (PMID 40904650, 2025). "The most used diabetes medications were metformin (95.0%), followed by sodium-glucose transport protein 2 (SGLT2) inhibitors (82.5%), sulfonylureas (47.5%), and dipeptidyl peptidase-4 (DPP-4) inhibitors (40.0%)." (PMID 41010617, 2025). "The findings suggest that the interplay between DPP-4 and peptides such as PYY, NPY, and PP may play a critical role in the development of obesity- and diabetes-related gastrointestinal complications." (PMID 40142315, 2025). "In light of these initial insights and the lack of definitive information on the impact of DPP4 inhibitors on brain pathways governing cognitive functions in diabetes, we opted to undertake this study." (PMID 38860903, 2025). "This study aimed to evaluate the periodontal status and levels of dipeptidyl peptidase-4 (DPP-4) and galectin-3 (Gal-3) in gingival crevicular fluid (GCF) of patients with periodontitis, heart failure (HF), and diabetes, exploring their potential as biomarkers for disease association." (PMID 40429343, 2025). "Despite the widespread use of biguanide drugs and DPP-4 inhibitors in the management of diabetes, there is a notable absence of direct comparative studies evaluating their cost-effectiveness in Japan." (PMID 39121166, 2024). "On the other hand, some diabetes medications, like the dipeptidyl peptidase-4 inhibitor sitagliptin, suppress CXCL5 and do not hasten the development of intestinal neoplasia in mice." (PMID 38884019, 2024).
diabetes (continued). "Saxagliptin, a competitive inhibitor of dipeptidyl peptidase-4 (DPP-4), stands as a cornerstone in diabetes management, enhancing insulin production by elevating glucagon-like peptide-1 (GLP-1) levels and promoting the conversion of GLP-1 into its inactive form." (PMID 38399334, 2024). "In animal models of diabetes, these powerful, selective, non-covalent inhibitors induced lasting reductions in plasma DPP-4 activity and blood glucose levels after a single oral dosage." (PMID 40066124, 2024). "The study confirmed that alogliptin, as a DPP-4 inhibitor, does not increase the incidence of major cardiovascular events, reassuring clinicians that the drug can be used safely in patients with diabetes and recent ACS." (PMID 39768866, 2024). "As the incidence of diabetes has increased, new drug classes, including glucagon-like peptide-1 (GLP-1) receptor agonists, sodium-glucose cotransporter 2 (SGLT2) inhibitors, and dipeptidyl peptidase-4 (DPP-4) inhibitors, have been rapidly developed and widely applied." (PMID 39834827, 2024). "Effective blood glucose management is essential, and sitagliptin (SITG), a dipeptidyl peptidase-4 (DPP-4) inhibitor, may offer neuroprotective benefits in type 2 diabetes mellitus (T2DM)." (PMID 39766390, 2024). "Natural DPP-4 inhibitors from Coptis chinensis were discovered in this work, which will facilitate the development of safe and effective DPP-4 inhibitors and reveal active ingredients in Coptis chinensis for treating diabetes." (PMID 38792165, 2024). "Commonly used anti-diabetic drugs among the diabetes cohort (metformin, sulfonylurea, insulin, and dipeptidyl peptidase-4 inhibitors) were not ranked among the top fifteen important variables." (PMID 39797086, 2024). "Furthermore, in our previous study, we compared the efficacy of miR-10b mimic against diabetes in HFHSD-induced diabetic mice with antidiabetic medications [insulin, liraglutide, DPP-4 inhibitor (sitagliptin), and metformin]." (PMID 38396943, 2024). "By inhibiting DPP-4 enzyme activity, these agents potentiate the actions of incretin hormones, namely glucagon-like peptide-1 (GLP-1) and gastric inhibitory polypeptide (GIP), addressing key pathophysiological aspects of diabetes." (PMID 39737272, 2024). "The remaining three studies without MMSE baseline or specific values suggested that DPP‐4 inhibitors can significantly improve cognitive function in patients with type 2 diabetes mellitus compared with other oral hypoglycemic agents." (PMID 37147888, 2023). "This section of the review enumerates the possible therapeutic mechanisms for AD of metformin, GLP-1 receptor agonists, DPP4 inhibitors, insulin, and SGLT2 inhibitors, all of which are widely applied to patients with diabetes according to official Clinical Guidelines." (PMID 36909158, 2023). "Combination of HDAC inhibitor vorinostat with the dipeptidyl peptidase-4 (DPP-4) inhibitor MK-626 increased β-cell mass without preventing diabetes." (PMID 37008937, 2023). "Therefore, the combination prescription rate of DPP-4 inhibitors and SGLT-2 inhibitors is high for blood glucose control in patients with diabetes mellitus." (PMID 37111730, 2023). "Our primary focus will be on elucidating the metabolic and molecular links between diabetes and Alzheimer’s disease and assessing the potential role of antidiabetic drugs including GLP-1 analogs, SGLT2 inhibitors, and DPP4 inhibitors, in the context of Alzheimer’s disease." (PMID 38002034, 2023). "Dipeptidyl peptidase-4 (DPP-4) inhibitors have exceptional safety and efficacy characteristics and are commonly employed to treat patients suffering from chronic kidney disease and diabetes mellitus as a comorbidity." (PMID 38034250, 2023). "Apart from triumph in developing several potent drugs used in therapy for diabetes mellitus (DM) by shielding GLP-1 degradation, DPP-4 inhibitors could be much more beneficial in a broader spectrum of indications." (PMID 37570832, 2023).
diabetes (continued). "This trial suggested that although DPP-4 inhibitor did not significantly improve the clinical conditions of COVID-19 patients with diabetes, the inhibitor also did not have any negative effect on their condition." (PMID 37064327, 2023). "Caffeic acid and the ethanolic extract of spent coffee grounds could potentially act as dual inhibitors targeting DPP-4 and MMP-9 as alternative treatments for type 2 diabetes mellitus and diabetic foot ulcers." (PMID 37894660, 2023). "Substrate-based DPP-4 inhibitors and non-substrate-based DPP-4 inhibitors refer to drugs used to treat diabetes." (PMID 37570832, 2023). "As DPP-4 inhibition mainly supports physiological roles of endogenous GLP-1, these inhibitors may be of significant relevance in curing T2DM or even pre-diabetes, but this remains to be confirmed in comprehensive clinical trials." (PMID 37287751, 2023). "While the effect of DPP4 on VSMCs is not characterized, DPP4 inhibitors, known as gliptins, are clinically used to treat diabetes." (PMID 37097759, 2023). "Furthermore, the incidence of PD was significantly reduced in diabetic patients using certain diabetes drug classes, such as glucagon-like peptide-1 (GLP-1) receptor agonists and GLP-1-degrading enzyme dipeptidyl peptidase 4 inhibitors." (PMID 37867511, 2023). "There are several treatments currently available for diabetes, including sodium-glucose cotransporter-2 (SGLT2) inhibitors, dipeptidyl peptidase-4 (DPP-4) inhibitors, biguanides, thiazolidinediones (TZDs), and glucagon-like peptide-1 receptor agonists (GLP-1RAs)." (PMID 37090383, 2023). "DPP-4 inhibitor could suppress gluconeogenic gene expression through the inhibition of CREB phosphorylation and CRTC2 expression in mice with diabetes." (PMID 36476135, 2022). "These networks of drug-disease interactions (DDSIs) and target-disease interactions (TDSIs) revealed a greater share of patients with diabetes and cardiac co-morbidities in the non-severe cohort treated with dipeptidyl peptidase-4 (DPP4) inhibitors." (PMID 36145576, 2022). "In db/db mice, treatment with a combination of DPP-4 inhibitor and SGLT2 inhibitor exerted more beneficial effects on β-cell mass, function and maintenance of β-cell identity markers in early (7-week old) than the advanced (16-week old) phase of diabetes." (PMID 35180212, 2022). "Further controlling confounding factors, long-term studies are needed to confirm the effect of DPP4 inhibitors on osteoporotic fracture in none-diabetes, non-menopausal, and different levels of obesity population." (PMID 35586625, 2022). "Diabetes mellitus and DPP-4 inhibitor medications did not affect the fluorescence intensities after GGT-HMRG or DPP-HMRG application." (PMID 35897725, 2022). "In the open field test, 14-days treatment with new adamantane derivatives or DPP4 inhibitors did not affect the locomotor activity of mice when compared to diabetes mice." (PMID 35468904, 2022). "Many research reports indicated that the natural antioxidants could inhibit biological enzymes such as Dipeptidyl Peptidase IV (DPP-4), α-amylase, and α- glycosidase which involved in diabetes mellitus type 2." (PMID 35620596, 2022). "Inhibition of dipeptidyl-peptidase 4 (DPP-4) in diabetic fatty rats reduced senescence along with an increase in the levels of glucagon-like peptide 1 (GLP-1), an antidiabetic hormone, providing additional evidence for increased senescence in diabetes." (PMID 35574460, 2022). "On an optimistic note, several new therapeutic approaches are now available for the management of diabetes in adults, such as GLP1 receptor agonists, SGLT2 inhibitors, and DPP4 inhibitors, that have also been shown to have a favorable impact on cardiorenal outcomes." (PMID 34913986, 2022). "Otherwise, the new class of antidiabetic drugs dipeptidyl peptidase 4 (DPP-4) inhibitors can safely be used in patients with diabetes non-insulin-dependent and ESRD." (PMID 35329847, 2022).
diabetes (continued). "Strategies in the management of diabetes include the inhibition of α-amylase, α-glucosidase, glucosidase, glycogen synthase kinase 3β (GSK-3β), lipase, aldose reductase, protein tyrosine phosphatases 1B (PTP1B), and dipeptidyl peptidase IV (DPP-4)." (PMID 36176638, 2022). "Contrary to the proband, diabetes in the father was polygenic-like type 2 diabetes, as it was diagnosed in adulthood and was treated with metformin and DPP4 inhibitor without any insulin." (PMID 35227307, 2022). "Several clinical trials of evogliptin administration among healthy subjects without diabetes showed good tolerability within the dose range of 1.25–60 mg and dose-dependent DPP-4 inhibition: no subjects developed hypoglycemia." (PMID 33401457, 2021). "The shift away from sulfonylureas may also reflect an international transition toward newer diabetes treatments such as SGLT-2 inhibitors, DPP-4 inhibitors and GLP-1 agonists." (PMID 34911481, 2021). "In addition, the DPP4/GLP-1 and NRF2/HO-1 systems are involved in ROS scavenging in diabetes and IRI." (PMID 33928135, 2021). "CD26/DPP4 exerts its peptidase activity towards various proteins, such as incretin hormones, and CD26/DPP4 inhibitors have been developed as therapeutic agents for diabetes." (PMID 34944016, 2021). "In our studies, we found that ACE2 and DPP4 were positively connected irrespective of the pancreatic nature, i.e., normal, cancer and diabetes." (PMID 33796097, 2021). "In this regard, this study is the first to compare the cardioprotective effects directly between SGLT2 inhibitors and DPP-4 inhibitors without metformin use in patients with early-stage diabetes without CVD that includes heart failure." (PMID 33530982, 2021). "We conducted an extensive literature search using keywords of oxidative stress, diabetes mellitus, glucagon-like peptides, GLP-1 receptor agonist, and DPP-4 Inhibitor in databases such as PubMed, Scopus, the Web of Science, and Google Scholar between 2002 and 2020." (PMID 34007411, 2021). "We then further determine the effects of diabetic and non-diabetic plasma on plasma DPP4 activity in diabetes." (PMID 34043673, 2021). "Interestingly, we found that DPP4 expression was significantly increased among the proteins regulated by YGD, and this protein was closely related to diabetes." (PMID 34641785, 2021). "DPP4 activation by the spike protein as seen in MERS-CoV may also be important in COVID-19, especially considering the role of diabetes." (PMID 33562193, 2021). "Studies on natural DPP-4 inhibitors offer a powerful means of developing novel treatments for T2DM, and it is hoped this review will help researchers searching for safer, natural DPP-4 inhibitors for the treatment of diabetes." (PMID 34203048, 2021). "Second, the database did not contain data on diabetes duration, or the duration of taking DPP-4 inhibitors." (PMID 34222054, 2021). "Further large-scale, blinded, placebo-controlled randomized clinical trials are needed to confirm the results and to explore possible applications of DPP-4 inhibitors in different stages of the disease in patients with and without diabetes." (PMID 35002970, 2021). "Therefore, we aimed to elucidate the effects of DPP-4 inhibitor and/or SGLT2 inhibitor on β-cell mass and function and compared their effects between in an early and advanced phase of diabetes." (PMID 34373487, 2021). "Contrary to what has been shown in patients with diabetes and advanced colorectal or airway cancers, exposure to DPP4 inhibitors did not lead to statistically significant improvement in PFS in patients with advanced-stage prostate cancer." (PMID 34055551, 2021). "Due to the exclusion of individuals with previously known and treated diabetes, we can rule out the effects of antidiabetic medications on DPP4 activity." (PMID 33538983, 2021). "The increase was primarily attributable to increased use of DPP-4 inhibitors, as the use of other diabetes drugs was minimal (data not shown)." (PMID 34911481, 2021).